TPH1 (tryptophan hydroxylase 1)
Diseases named in the same sentence as TPH1 in open-access papers (continued):
Sharing a sentence is not in itself a finding about the gene and the disease.
lung carcinoma (1 paper, 2018). "Other NETest markers involved in growth factor signaling and genes involved in the regulation of the neuroendocrine phenotype e.g., cell secretion and granule transport, or other canonical neuroendocrine marker genes, e.g., TPH1 and NAP1L1 were also scarcely detectable in lung cancers." (PMID 29467960, 2018).
macrocytic anemia (1 paper, 2013). Anemia that is characterized by increased red blood cell volume. "In depth analysis of the TPH1 knockout mouse revealed that they develop a phenotype of macrocytic anemia resulting from both an ineffective erythropoiesis in the bone marrow and a reduced half-life of their circulating red blood cells (RBC)." (PMID 24358245, 2013). "Previous analysis of the TPH1 knockout (TPH1−/−) mouse revealed that they develop a phenotype of macrocytic anemia with a reduced half-life of their circulating red blood cells (RBC)." (PMID 24358245, 2013).
mastocytoma (1 paper, 2023). A localized tumor composed of sheets of mast cells without atypia. "We provide evidence that TPH1 mRNA levels are increased in response to increased exogenous GLN in mouse mastocytoma cells via a stabilization of TPH1 mRNA due to the activity of the p38 MAP kinase." (PMID 36331742, 2023). "In this report, we describe the mechanism for accumulation of TPH1 mRNA in cultured P815-HTR mouse mastocytoma cells; it should be noted that TPH enzymatic activity in P815-HTR cells has been previously reported." (PMID 36331742, 2023). "For P815-HTR cells, a transformed mouse mastocytoma cell line, there are reasonable levels of TPH1, allowing a study of TPH1 message regulation and the cells being used as a source of TPH1." (PMID 36331742, 2023). "We demonstrate that TPH1 mRNA is augmented upon exposure to exogenous GLN in mouse mastocytoma cells; this was via stabilization of TPH1 mRNA." (PMID 36331742, 2023). "Expression changes for tryptophan hydroxylase 1 (TPH1), the rate-limiting enzyme in serotonin synthesis, by environmental glutamine (GLN) were examined in mouse mastocytoma-derived P815-HTR cells." (PMID 36331742, 2023).
medullary thyroid cancer (1 paper, 2025). "Collectively, Tph1-mediated 5-HT synthesis played an important role in promoting the liver metastasis of pleiotropic NE malignancies, including NEPC, SCLC, and medullary thyroid cancer by facilitating NET formation." (PMID 39903533, 2025).
myeloid leukemia (1 paper, 2022). A clonal proliferation of myeloid cells and their precursors in the bone marrow, peripheral blood, and spleen. "The expression of TPH1 in the human myeloid leukemia mononuclear cells (THP-1) cells was validated; hence, the THP-1 cells were employed as a positive control." (PMID 36037970, 2022).
myocardial infarction (1 paper, 2024). Gross necrosis of the myocardium, as a result of interruption of the blood supply to the area, as in coronary thrombosis. "A cardiovascular study showed lower myocardial TPH-1 mRNA and plasma 5-MTP levels 24 and 48 h after coronary artery ligation, suggesting that the protective effects of 5-MTP were attenuated post-myocardial infarction (MI)." (PMID 38683422, 2024).
neuroendocrine tumors (1 paper, 2012). "Notably, the expression of genes found to be typically active in neuroendocrine tumors (Hofsli gene signature) were also significantly diminished in 424GC cells, including genes encoding neuroendocrine markers such as chromogranin A, dopa decarboxylase (DDC) and TPH1." (PMID 22253802, 2012).
opioid dependence (1 paper, 2021). "Studies have revealed the association of TPH1 A218C with impulsivity, suicidality, and opiate dependence." (PMID 34900485, 2021). "The present study reports on the association of 5HTTLPR, STin2, TPH1 (A218T), and TPH2 (G703T) polymorphisms of the serotonergic pathway with self-harm, depressive symptoms, impulsiveness, and aggression in opioid dependence." (PMID 34900485, 2021).
pancreatic endocrine tumour (1 paper, 2009). "Thus, ASCL1 negatively regulates DKK1 and TPH1 in BON1 pancreatic endocrine tumour cells." (PMID 19744316, 2009).
Parkinson disease (1 paper, 2013). A progressive degenerative disorder of the central nervous system characterized by loss of dopamine producing neurons in the substantia nigra and the presence of Lewy bodies in the substantia nigra and locus coeruleus. "Interestingly, the robust decrease in stride length found in the Tph1 (−/−) is similar to that in a recently published C57BL/6J mouse model of Parkinson's disease using 1-methyl-4-phenyl-1,2,3,6-tetrahydropyridine to induce lesions of the substantia nigra." (PMID 23516593, 2013).
peritonitis (1 paper, 2014). Inflammation of the peritoneum (tissue that lines the abdominal wall and covers most of the organs in the abdomen). "Accordingly, Tph1−/− mice display reduced neutrophil extravasation in thioglycollate-induced peritonitis." (PMID 24520366, 2014).
Right ventricular hypertrophy (1 paper, 2022). In this case the right ventricle is more muscular than normal, causing a characteristic boot-shaped (coeur-en-sabot) appearance as seen on anterior- posterior chest x-rays. "Tph1 KO mice were not protected from hypoxia‐induced alveolar simplification, decreased pulmonary vascular density, or right ventricular hypertrophy, but displayed attenuation to hypoxia‐induced RVSP elevation compared with WT mice." (PMID 36200294, 2022).
rosacea (1 paper, 2025). A chronic erythematous skin disorder that affects the face. "Analysis revealed the concentration of 5-HT along with the mRNA expression of TPH1 (the key enzyme of 5-HT synthesis) was significantly elevated in rosacea-like mice." (PMID 40243950, 2025). "In vivo analysis demonstrated that the levels of 5-HT and TPH1 mRNA expression were elevated in rosacea-like mice, implying that LL-37 promoted biosynthesis and secretion of 5-HT, which could lead to a bad inflammatory feedback loop." (PMID 40243950, 2025).
sarcopenia (1 paper, 2025). Progressive decline in muscle mass due to aging which results in decreased functional capacity of muscles. "A metagenomics analysis from the Xiangya Sarcopenia Study demonstrated that the abundance of Clostridium, an enhancer of the expression of TPH1 in EC cells of the gut, is increased in the sarcopenia group." (PMID 39926388, 2025).
scoliosis (1 paper, 2025). A congenital or acquired spinal deformity characterized by lateral curvature of the spine. "Tryptophan hydroxylase (TPH1 rs10488682), insulin-like growth factor (IGF1 rs5742612), neurotrophin 3 (NTF3 gene promoter at rs11063714), interleukin-17 receptor C (IL17RC rs708567), melatonin receptor 1B (MTNR1B rs4753426) were identified as risk factors for scoliosis curve progression." (PMID 39781499, 2025).
sleep-disordered breathing (1 paper, 2023). "A tendency to sleep-disordered breathing seemed to co-occur with lower blood serotonin and higher TPH1 levels." (PMID 37479853, 2023).
thrombotic disorders (1 paper, 2021). "This gave ground to attempts of gene therapy targeting TPH1 down-regulation with the aim of treating thrombotic disorders." (PMID 34680558, 2021).
thymoma (1 paper, 2026). A neoplasm arising from the epithelial cells of the thymus. "In thymomas, the transcript levels of autoantigens that are frequently targeted by autoantibodies (CYP21, CYP17, TPH1, TH, TPO) did not correlate with AIRE expression." (PMID 41461613, 2026).
Venous thrombosis (1 paper, 2025). Formation of a blood clot (thrombus) inside a vein, causing the obstruction of blood flow. "On the other hand, the Tph1-/- group had the largest and most frequent venous thrombosis in this study." (PMID 40821747, 2025).
tumor (38 papers, 2009 to 2025). "Consistently, the GO enrichment analysis also indicated that the cell adhesion molecule signaling was involved in TPH-1 associated tumor progression." (PMID 35473609, 2022). "Comprehensively, we identified a novel risk score based on OV cancer amino acid metabolism, the risk score predicted survival and tumor stages with high accuracy, and the oncogenic role of the risky gene TPH1 was experimentally validated." (PMID 35783506, 2022). "β-catenin, together with the transcription factor ZBP-89, further enhances TPH1 expression, forming a feedback loop that maintains high serotonin levels and supports tumor progression." (PMID 41375042, 2025). "While traditional CAR T cells reduce tumor volume by approximately 32% on day 23, Tph1‐CAR T cells achieve a tumor reduction of approximately 78%, indicating markedly stronger antitumor activity." (PMID 40937192, 2025). "More recently, it was also shown that Tph1 was induced in response to IL-2 in T cells in tumor microenvironment, leading to AhR nuclear translocation." (PMID 38509264, 2024). "The orthotopic tumor tissues were collected and the expression of TPH1 was assessed using immunofluorescence." (PMID 36172162, 2022). "Intriguingly, tumor cells in the M group showed elevated expression of TPH1 when compared to those in the NM group." (PMID 36172162, 2022). "Consistent with in vitro results, a rapid tumor growth curve was observed in TPH-1 overexpressing LN229 bearing mice relative to the vec-LN229 bearing mice." (PMID 35473609, 2022). "Results showed that TPH1 mRNA was lower while TPH2 mRNA was increased in colorectal tumors than in non-tumor tissue." (PMID 36408175, 2022). "It has also been demonstrated that TPH1 expression is increased during tumor progression, which corresponds to increased serotonin synthesis." (PMID 33525332, 2021). "Male fish had higher levels of phoso-Tph1 than female fish across all three comparing groups and male xmrk-expressing tumor had a higher phoso-Tph1 level than Myc-expressing tumor." (PMID 28871112, 2017). "We found that 5-HT was present in most of the tumor cells comprising the tumor sections suggesting that TPH1 is indeed active in the tumor cells." (PMID 27447971, 2016). "Segregating the cases crudely according to tumor size and according to T-stage (another size-based classification) showed an inverse relationship between tumor size (>20 mm) and TPH1 staining." (PMID 19903352, 2009). "Tumor cells metabolize tryptophan into 5-HT via the enzyme tryptophan hydroxylase 1 (TPH1)." (PMID 40666095, 2025). "The TPH1 expression is lower in tumor tissues than in normal tissues." (PMID 39309474, 2024). "They further suggest that TPH-1 facilitates tumor progression via autocrine serotonin signaling." (PMID 35473609, 2022). "Interestingly, TPH1 participated in mast cell-mediated immunosuppression, indicating its potential role in tumor-supporting and immunity depression." (PMID 35783506, 2022). "Additionally, L1CAM silencing also suppressed the pro-tumor effects induced due to TPH1 overexpression." (PMID 35473609, 2022). "Therefore, we sought to suppress TPH1 to interrupt the 5-HT/β-catenin/TPH1 signaling loop to suppress tumor growth and eliminate M tumor cells." (PMID 36172162, 2022). "The results indicate that 5-HT contributed to tumor progression induced by TPH1." (PMID 36172162, 2022). "Moreover, inhibition of TPH-1 by LX-1031 significantly suppressed the tumor growth and improved the outcomes of TMZ treatment." (PMID 35473609, 2022). "Nearly all the tumor cells expressed TPH1 and produced 5-HT." (PMID 34073226, 2021).
tumor (continued). "A question is whether the increased serotonin secretion upon the RV infection of EC tumor cells was a result of an accumulation of pre-made serotonin in secretory granules, or of increased TPH1 transcription and translation." (PMID 27459372, 2016). "To determine whether TPH1 is active in the tumor cells we enquired whether 5-HT is present in the tumor cells using an antibody specific to 5-HT." (PMID 27447971, 2016). "In order to see whether overexpression of Tph1 in d90 tumor tissue translates into higher serotonin blood levels in tumor-bearing mice, we measured serotonin serum concentrations in wildtype and CEA424-SV40 TAg-transgenic mice using ELISA." (PMID 22253802, 2012). "Cancer cells may target a number of factors that act to regulate the mitochondrial melatonergic pathway in tumor microenvironment cells, including tryptophan uptake, 14-3-3 isoforms, TPH1/2, serotonin uptake/metabolism, acetyl-CoA, AANAT, ASMT, P2Y1r and mGluR5 receptor, as well as the AhR." (PMID 36613754, 2022). "Interestingly TPH1 protein levels are increased in primary tumors that had metastasized to lymph nodes suggesting a relationship between tumor aggressiveness and increased 5-HT levels in tumor cells." (PMID 27447971, 2016). "Silencing TPH‐1 or 5‐HTR3A, or treatment with the TPH‐1 inhibitor 4‐chloro‐L‐phenylalanine or the 5‐HTR3A antagonist tropisetron, alleviates tumor development." (PMID 41415714, 2025). "In a pancreatic ductal adenocarcinoma (PDAC) study, elevated levels of TPH1 and decreased levels of monoamine oxidase A (MAOA), a serotonin‐degrading enzyme, were reported, correlating with tumour stage, size and poor prognosis." (PMID 39223878, 2024). "In our study, the TPH1 inhibitor PCPA was combined with the chemotherapeutic agent PTX, which revealed improved tumor-suppressive effects in vitro and in vivo." (PMID 36172162, 2022). "To retard the sustained tumor growth induced by TPH-1, we combined TMZ with the TPH-1 inhibitor, LX-1031, and treated the TPH-1 overexpressing LN229 bearing mice." (PMID 35473609, 2022). "TPH1, 5-HT and SERT were also expressed in most of the tumor cells in HCC1954 tumor xenografts and tumorspheres." (PMID 28404880, 2017). "Structurally unrelated selective antagonists affecting the activity of TPH1, SERT and a minimum of 7 individual 5-HT receptors reduced the frequency of BTIC as revealed by sphere-forming or tumor cell transplantation assays." (PMID 28404880, 2017). "platelet-secreted metabolites including tryptophan hydroxylase 1 (TPH1) and prostaglandin E2 (PGE2) synergistically enhance tumor PD-L1 expression through STAT3/NF-κB signaling activation, while pharmacological inhibition of these pathways enhances immune cell infiltration." (PMID 40514754, 2025). "Thus, TPH-1 overexpressing LN229 cells were subcutaneously implanted into immunodeficient mice, and the tumor volumes were recorded." (PMID 35473609, 2022). "Despite the substantial research efforts, a clear understanding of the role of TPH-1 in tumor progression is lacking." (PMID 35473609, 2022). "Most patients had little to no TPH1 and its product serotonin in their tumor samples, while nearby normal tissue displayed TPH1-positive cells, which are secretory epithelial cells specialized in producing serotonin, named enterochromaffin cells (ECs)." (PMID 31416966, 2019). "In addition, compared to vehicle-treated control group, TPH1 and VEGF protein expression was suppressed by BJ-1113 in MDA-MB-231 effluc tumor." (PMID 27871326, 2016). "Tumours with high or heterogeneous expression showed a somewhat lower TPH1 expression than control non-tumourous pancreatic tissue." (PMID 19744316, 2009). "A recent retrospective study analysed tumours from 23 CCA patients treated with GemCis and found that tumour TPH‐1 expression did not predict treatment response." (PMID 39223878, 2024).
tumor (continued). "However, reduced tumor number and load of DSS/AOM-induced tumors were also observed in Tph1 KO mice (without statistical significance), and this reduction was significant in DKO (Tph1 and Tph2 KO) mice, suggesting that EC cells may also participate in CRC progression." (PMID 36408175, 2022).
cancer (15 papers, 2009 to 2025). A tumor composed of atypical neoplastic, often pleomorphic cells that invade other tissues. "Finally, we screened out 4 PRISM drugs with lower IC50 in the high-risk group and validated the oncogenic role of TPH1 in OV cancers." (PMID 35783506, 2022). "Co-IF staining for H3cit and MPO revealed that Tph1 KD in NEPC organoids led to suppressed hepatic NET formation in nearby areas of metastatic cancer cells compared with scrambled shRNA–transfected counterparts." (PMID 39903533, 2025). "The clone formation assay results showed that the clone assay of OV cancer cells in the TPH1-si-RNA-#1 and TPH1-si-RNA-#2 groups was depressed." (PMID 35783506, 2022). "It has been reported EZH2 and 5-HT derived from peripheral TPH1 in cancer tissues independently contributes to cancer malignancy by stimulating cancer cell proliferation and invasion." (PMID 34771469, 2021). "A549 cancer cells express abundant TPH-1 but very low levels of HIOMT298 and hence produce very low level of 5-MTP." (PMID 33925793, 2021). "As cancer cells express abundant TPH-1 but are unable to convert 5-HTP to 5-MTP, reduced 5-MTP levels are attributed to the defective expression of HIOMT." (PMID 33925793, 2021). "However, the mechanism underlying the regulation of TPH1 expression in cancer remains unclear." (PMID 27144435, 2016). "Similar to the expression pattern we had seen previously in the cell lines, TPH1 staining intensity was significantly elevated in the cancer cell lines, compared with normal breast tissue." (PMID 19903352, 2009). "Recently, some reports have shown that TPH1 also plays a role in cancer progression." (PMID 39309474, 2024). "It is worth mentioning that the posttranscriptional control of TPH1 and the diurnal change of TPH1 activity in the central nervous system have been shown; although, there is no known evidence regarding their association with cancer." (PMID 38397058, 2024). "Similarly, we found that the knockdown of TPH1 inhibited OV cancer clone formation and migration ability, which is consistent with previous findings." (PMID 35783506, 2022). "Similarly, the transwell results also presented that TPH1 knockdown inhibited the OV cancer cell migration and invasion." (PMID 35783506, 2022). "Recently, several reports have suggested that TPH1 also has a role in cancer progression." (PMID 27144435, 2016). "TPH1 was highly expressed in SE cancer tissues compared with adjacent normal tissues." (PMID 27144435, 2016). "This conclusion is based on the observations that; 1) TNBCs (MDA-MB-231, HCC-1395, and Hs578T) expressed higher levels of TPH1 and 5-HT7 receptor, and secreted more 5-HT than hormone-positive cells (MCF-7 and T47D), 2) silencing of TPH1 or 5-HT7 receptor blocked cancer invasion and proliferation." (PMID 27871326, 2016). "Increased TPH1 expression in cancer cell lines was confirmed on the microarray specimens." (PMID 19903352, 2009). "An important insight was the observation that there was not a simple linear association between TPH1 expression and cancer stage." (PMID 19903352, 2009). "Of note, the THP1 posttranscriptional regulation and the diurnal variation of TPH1 activity in the central nervous system have been demonstrated, but none seems to be reported about cancer." (PMID 33178611, 2020). "Treatment with BJ-1113 significantly suppressed the 5-HT-enhanced expressions of TPH1, MMP-9, and VEGF, and consequently, the secretions of VEGF and 5-HT, suggesting that BJ-1113 suppresses cancer progression by inhibiting VEGF expression and the autocrine function of 5-HT." (PMID 27871326, 2016). "Given the strong antiangiogenic activity of BJ-1113 against VEGF, the inhibitory effects of BJ-1113 on the expressions of TPH1 and VEGF in MDA-MB-231 cells indicate BJ-1113 exhibits the properties required of an anti-cancer agent for tumors resistant to anti-VEGF therapy." (PMID 27871326, 2016).